KRT79 (keratin 79)
Synonyms: K6L; KRT6L
Tractability: PROTAC: ubiquitination databases record sites on it.
Gene: Protein-coding gene on chromosome 12 (52,821,408 to 52,834,311, reverse strand). Ensembl gene ENSG00000185640.
Pathways (Reactome):
Developmental Biology: Formation of the cornified envelope; Keratinization
Gene Ontology:
Molecular function: enzyme binding; protein binding; structural constituent of skin epidermis
Biological process: intermediate filament organization; keratinization
Cellular component: extracellular exosome; cytosol; keratin filament
Genetic constraint (gnomAD): Loss-of-function variants: 52 observed, 51.58 expected, observed/expected ratio (o/e) 1.01, 90% interval 0.81 to 1.27. The upper end of that interval is the gene's LOEUF score, 1.27, which puts it in group 5 of 6, group 1 being the genes least tolerant of losing a copy. Missense variants: 728 observed, 720.05 expected, observed/expected ratio (o/e) 1.01, 90% interval 0.95 to 1.08. Synonymous variants: 312 observed, 301.71 expected, observed/expected ratio (o/e) 1.03, 90% interval 0.94 to 1.14.
Homologues: Orthologues: chimpanzee KRT79 (98% identical), macaque KRT79 (95% identical), pig KRT79 (84% identical), guinea pig KRT79 (84% identical), mouse Krt79 (83% identical), rat Krt79 (77% identical). Paralogues in human: KRT6A (65% identical), KRT3 (64% identical), KRT6B (64% identical), KRT6C (64% identical), KRT5 (64% identical), KRT75 (62% identical), KRT76 (62% identical), KRT4 (60% identical), KRT1 (59% identical), KRT2 (59% identical), KRT77 (56% identical), KRT73 (55% identical), and 56 more.
Diseases named in the same sentence as KRT79 in open-access papers:
KRT79 is named in the same sentence as 10 diseases in open-access papers, as found by Europe PMC text mining. Sharing a sentence is not in itself a finding about the gene and the disease. The quoted sentences say what the papers report.
liver disease (2 papers, 2023). "Taken together, these results demonstrate that hepatic Krt79 is a PPARA target gene and that KRT79 can be used as a biochemical or histological diagnostic biomarker for human liver diseases." (PMID 36796223, 2023). "Thus, KRT79 may be considered as a diagnostic marker for human liver diseases." (PMID 36796223, 2023). "In the liver, KRT79 is controlled by PPARA and is highly correlated with liver injury, making it a potential diagnostic marker for human liver disease." (PMID 38017403, 2023).
acne (1 paper, 2020). An inflammatory process of the sebaceous glands which is characterized by comedones, nodules, papules and/or pustules on the skin. "Indeed, expression of KRT79 was lost in five out of seven comedone samples from acne patients." (PMID 33082341, 2020).
asthma (1 paper, 2024). "Another male-specific pQTL rs11207327 linked with CD5 levels also modulates the expression of genes (JUN, KRT79, TACSTD2), and it is associated with diseases and traits (Asthma, self-reported haemorrhoids and treatment with estriol product)." (PMID 38326779, 2024).
hepatoma (1 paper, 2023). "Furthermore, basal expression level of Krt79 in Hepa-1 cells originated mouse hepatoma was significantly elevated compared to primary hepatocytes." (PMID 36796223, 2023).
cancer (2 papers, 2023 to 2024). A tumor composed of atypical neoplastic, often pleomorphic cells that invade other tissues. "Several members of the KRT gene family, including the evolutionarily older KRT8, KRT18, KRT19, KRT23, KRT79, KRT80 and KRT222, were shown to be differentially regulated in diverse cancer types." (PMID 36949761, 2023). "Several KRT genes, including the phylogenetically older KRT8, KRT18, KRT19, KRT23, KRT79, KRT80 and KRT222, were found to be differentially expressed in diverse types of cancers." (PMID 36949761, 2023).
tumor (1 paper, 2020). "Studies have shown that KRT79 is involved in cell migration and tube generation, and we speculate that it may affect the tumor angiogenesis." (PMID 33335850, 2020).
KRT79 also shares sentences with these, for which no sentence is quoted: colorectal cancer (1 paper); haemorrhoids (1); leukemia (1); sarcoma (1).